RYR1 (ryanodine receptor 1)
Description:
Cytosolic calcium-activated calcium channel that mediates the release of Ca(2+) from the sarcoplasmic reticulum into the cytosol and thereby plays a key role in triggering muscle contraction following depolarization of T-tubules. Repeated very high-level exercise increases the open probability of the channel and leads to Ca(2+) leaking into the cytoplasm. Can also mediate the release of Ca(2+) from intracellular stores in neurons, and may thereby promote prolonged Ca(2+) signaling in the brain. Required for normal embryonic development of muscle fibers and skeletal muscle. Required for normal heart morphogenesis, skin development and ossification during embryogenesis (By similarity).
Synonyms: RYR-1; RYDR; RYR; PPP1R137; CCO; CMYO1A; CMYO1B; CMYP1A; CMYP1B; KDS; MHS; MHS1; SKRR
Tractability: Small molecule: an approved drug acts on it; it belongs to a druggable protein family. Antibody: its Gene Ontology location is reachable by antibodies, with high confidence; UniProt predicts a signal peptide or a membrane-spanning region. PROTAC: ubiquitination databases record sites on it; a small molecule that binds it is known.
Target class: Ligand-gated ion channel; Ion channel; Ryanodine receptor
Safety:
Unwanted effects reported when the protein is acted on. In parentheses: how it was acted on, where the effect was seen, and who reports it.
malignant hyperthermia (source: ClinPGx)
malignant hyperthermia susceptibility (source: ClinPGx)
risk to statin-related myopathy (source: ClinPGx)
Gene: Protein-coding gene on chromosome 19 (38,433,691 to 38,595,273, forward strand). Ensembl gene ENSG00000196218.
Subcellular location: Sarcoplasmic reticulum membrane
Subcellular location (Human Protein Atlas): Golgi apparatus; Vesicles; Cytosol
Pathways (Reactome):
Muscle contraction: Ion homeostasis
Transport of small molecules: Stimuli-sensing channels
Gene Ontology:
Molecular function: calcium-induced calcium release activity; ryanodine-sensitive calcium-release channel activity; ATP binding; calcium channel activity; calcium ion binding; calmodulin binding; intracellularly gated calcium channel activity; voltage-gated calcium channel activity; enzyme binding; monoatomic ion channel activity; protease binding
Biological process: calcium ion transmembrane transport; cellular response to caffeine; release of sequestered calcium ion into cytosol; response to hypoxia; calcium ion transport; cellular response to calcium ion; muscle contraction; ossification involved in bone maturation; outflow tract morphogenesis; protein homotetramerization; regulation of cytosolic calcium ion concentration; release of sequestered calcium ion into cytosol by sarcoplasmic reticulum; response to caffeine; skeletal muscle fiber development; skin development; striated muscle contraction; calcium-mediated signaling; intracellular calcium ion homeostasis; monoatomic ion transport; transmembrane transport
Cellular component: cell cortex; cytoplasm; extracellular exosome; I band; plasma membrane; sarcoplasmic reticulum membrane; calcium channel complex; junctional sarcoplasmic reticulum membrane; organelle membrane; ryanodine receptor complex; sarcolemma; sarcoplasmic reticulum; smooth endoplasmic reticulum; terminal cisterna; Z disc; junctional membrane complex; membrane; protein-containing complex; T-tubule
Genetic constraint (gnomAD): Loss-of-function variants: 336 observed, 570.76 expected, observed/expected ratio (o/e) 0.59, 90% interval 0.54 to 0.64. The upper end of that interval is the gene's LOEUF score, 0.64, which puts it in group 2 of 6, group 1 being the genes least tolerant of losing a copy. Missense variants: 6,006 observed, 6,918.6 expected, observed/expected ratio (o/e) 0.87, 90% interval 0.85 to 0.89. Synonymous variants: 2,781 observed, 2,828.5 expected, observed/expected ratio (o/e) 0.98, 90% interval 0.95 to 1.01.
Gene-disease validity (ClinGen):
ClinGen rates the evidence that RYR1 causes each of these diseases.
malignant hyperthermia, susceptibility to, 1 (autosomal dominant): Definitive.
RYR1-related myopathy (autosomal dominant; autosomal recessive): Definitive. A disorder of the musculoskeletal system caused by pathogenic variants in the RYR1 gene, which encodes the ryanodine receptor type 1 protein.
Homologues: Orthologues: chimpanzee RYR1 (99% identical), macaque RYR1 (97% identical), dog RYR1 (97% identical), mouse Ryr1 (96% identical), rat Ryr1 (96% identical), pig RYR1 (94% identical), guinea pig RYR1 (87% identical), rabbit RYR1 (84% identical), tropical clawed frog ryr1 (79% identical), zebrafish ryr1b (76% identical), zebrafish ryr1a (76% identical), Drosophila melanogaster RyR (45% identical), and 1 more. Paralogues in human: RYR2 (65% identical), RYR3 (65% identical), ITPR2 (13% identical), ITPR1 (13% identical), ITPR3 (13% identical).
Diseases named in the same sentence as RYR1 in open-access papers:
RYR1 is named in the same sentence as 263 diseases in open-access papers, as found by Europe PMC text mining. Sharing a sentence is not in itself a finding about the gene and the disease. The quoted sentences say what the papers report.
Malignant hyperthermia (137 papers, 2007 to 2025). Malignant hyperthermia is characterized by a rapid increase in temperature to 39-42 degrees C. Malignant hyperthermia may occur in response to either inhalational anesthetics such as halothane, to muscle relaxants such as succinylcholine, or to exercise. "Pathogenic mutations that render RyR1 channels dysfunctional are linked to malignant hyperthermia (MH), exercise-induced rhabdomyolysis, and a wide range of RyR1-related myopathies (RyR1-RMs), including central core disease (CCD)." (PMID 41392983, 2025). "This strategy was previously used to successfully reduce the formation of cores and susceptibility to malignant hyperthermia in mice carrying the human Y522S mutation in the RYR1 (YS mice) and in CASQ1-null mice." (PMID 41009681, 2025). "Mutations in the RYR1 gene, encoding the ryanodine receptor 1, have long been associated with neuromuscular disorders such as malignant hyperthermia (MH) and central core disease (CCD)." (PMID 40429823, 2025). "This study aimed to investigate the effect of a rare duplication in the RYR1 gene in the variability of the phenotype in Malignant Hyperthermia susceptibility, thereby contributing to the elucidation of its pathogenicity." (PMID 41300704, 2025). "Malignant hyperthermia (MH) is a rare pharmacogenetic disorder triggered by volatile anesthetics and succinylcholine, most often linked to pathogenic variants in RYR1, CACNA1S, and STAC3." (PMID 41300733, 2025). "In many instances, the RyR1 mutants associated with malignant hyperthermia susceptibility (MHS) are linked to the abnormal increase in CICR activity." (PMID 40460053, 2025). "Variants in RYR1 are implicated in malignant hyperthermia (MH), a rare hypermetabolic disorder characterized by constitutive activation of the RYR1 channel in response to a subset of anesthetic medications, producing prolonged skeletal muscle contraction." (PMID 41300733, 2025). "We aimed to investigate the effect of a rare duplication in the RYR1 gene with the variability of the Malignant Hyperthermia susceptibility phenotype." (PMID 41300704, 2025). "In fact, rs118192162, another RYR1 mutation associated with malignant hyperthermia, has been shown to increase catecholamine-induced arrythmias through mitochondrial Ca2+ overload." (PMID 40060969, 2025). "The European Malignant Hyperthermia Group (EMHG) currently recognises an ever-growing list of 66 pathogenic/likely pathogenic variants in RYR1 and two in CACNA1S (encodes α-subunit of the dihydropyridine receptor) for MH diagnosis." (PMID 38542460, 2024). "As the primary Ca2+ release channel in skeletal muscle sarcoplasmic reticulum (SR), mutations in type 1 ryanodine receptor (RyR1) or its binding partners underlie a constellation of muscle disorders, including malignant hyperthermia (MH)." (PMID 39304470, 2024). "Variants in the calcium release channel, ryanodine receptor isoform 1 (RYR1), are associated with malignant hyperthermia (MH), a pharmacogenetic disorder of skeletal muscle." (PMID 38542460, 2024). "Actionable variants in both cardiovascular disease-related and cancer-related genes affect more than 1% of the population and we also observed a high frequency of GPPs with variants in RYR1 (12%; 62/508) associated with Malignant hyperthermia." (PMID 39020067, 2024). "In pigs, a point mutation in the ryanodine receptor 1 (RYR1) gene has been determined to be the genetic cause of malignant hyperthermia resulting in PSE meat." (PMID 38731703, 2024). "Mutations in RYR1 have been associated with different diseases with both dominant and recessive inheritance: susceptibility to Malignant Hyperthermia, Central Core Disease Minicore, and Centronuclear Myopathy with External Ophthalmoplegia." (PMID 37510298, 2023). "Our data show that the three genes currently associated with malignant hyperthermia (RYR1, CACNA1S and STAC3) are all misregulated in groups 1 and 3, but not group 2." (PMID 36282542, 2023).
Malignant hyperthermia (continued). "Mutations in RYR1 are related to susceptibility to malignant hyperthermia and are shown to be the most common cause of exertional RM." (PMID 37510298, 2023). "In the previous report, two malignant hyperthermia-associated mutations, G4733E and R4736W in the S2–S3 loop particularly impaired RyR1 inhibition." (PMID 38159862, 2023). "Pathogenic variants in RYR1 related to malignant hyperthermia (MH) were detected in two (8.3%) participants." (PMID 36635046, 2023). "Susceptibility to malignant hyperthermia is another autosomal dominant skeletal muscle disorder caused by heterozygous pathogenic variants in RYR1 (OMIM #145600)." (PMID 36874254, 2022). "In particular, mutations in RYR1, the gene-encoding RyR1, are causative of malignant hyperthermia (MH; MIM #145600), central core disease (CCD; MIM #11700), specific forms of multi-minicore disease (MmD; MIM # 255320), and centronuclear myopathy." (PMID 35238775, 2022). "Variants within the RYR1 gene have a causative role in the development of malignant hyperthermia (MH), a rare, but serious condition characterized by sustained muscle contraction, hyperthermia, and rhabdomyolysis in response to halogenated anesthetics." (PMID 35698232, 2022). "CASQ1-knockout mice and mice carrying a mutation in RYR1 (Y522S) linked to human malignant hyperthermia susceptibility (MHS) both suffer lethal hypermetabolic episodes when exposed to halothane (MHS crises) and to environmental heat (heat stroke, HS)." (PMID 36010545, 2022). "Malignant hyperthermia (MH) is a very rare disease, in which symptoms are induced by a pharmacogenomic reaction, caused by genetic mutations in the ryanodine receptor 1 (RYR1) gene, which encodes a calcium channel protein." (PMID 33863374, 2021). "Mutations in the type 1 ryanodine receptor (RyR1), a Ca2+ release channel in skeletal muscle, hyperactivate the channel to cause malignant hyperthermia (MH) and are implicated in severe heat stroke." (PMID 34257294, 2021). "Other RYR1 mutations render the RyR1 channel hypersensitive to triggering agents in volatile anesthetics and induce excessive Ca2+ release from the SR, resulting in malignant hyperthermia (MH)." (PMID 34359900, 2021). "The second pathogenic variant was RYR1(NM_000540.3):c.6502G>A (p.Val2168Met), which is associated with malignant hyperthermia." (PMID 33597575, 2021). "Although many RYR1 mutations have been reported to meet the diagnostic criteria of the European Group of Malignant Hyperthermia (EMHG), our study validated only some of these mutations." (PMID 33490280, 2021). "Off-target drug effects can also occur without an immunological component, such as the interactions of anesthetics with the ryanodine receptor 1 (RYR1) protein causing malignant hyperthermia." (PMID 34316407, 2021). "Mutations in RyR1, the skeletal muscle isoform, can cause malignant hyperthermia (MH), central core disease (CCD), and other myopathies." (PMID 33547325, 2021). "Autosomal dominant mutations in RYR1 have been classically reported in patients with susceptibility to malignant hyperthermia (MH) and congenital central core disease (CCD)." (PMID 33170376, 2021). "Mutations in ryanodine receptor 1 (RyR1), a Ca2+ release channel in skeletal muscle, cause malignant hyperthermia (MH) and are involved in heat stroke." (PMID 34257294, 2021). "This increased sensitivity to halothane, conferred by these single amino acid changes in the ryanodine receptor, reflects the anaesthetic sensitivity of RYR1-associated malignant hyperthermia." (PMID 32174957, 2020). "Dominant mutations in the RYR1 gene are found in the majority of individuals with malignant hyperthermia susceptibility (MHS), an allelic disorder to CCD." (PMID 32456280, 2020). "This concept of compensated leak was proposed to explain normal basal [Ca2+]i in conjunction with Ca2+ leak from RyR1 due to a mutation found in malignant hyperthermia (Y522S)." (PMID 31468006, 2019).
Malignant hyperthermia (continued). "Previously, it was reported that a single RyR1 mutation L2867G that causes malignant hyperthermia (MH) can reduce the Tm of RyR1 Repeat34 by 13 °C." (PMID 31597572, 2019). "This includes patients who undertake regular high-intensity exercise or have mutations in the RyR1 associated with malignant hyperthermia." (PMID 31468006, 2019). "To date, approximately 30 mutations in the over 300 variations of the RYR1 gene have been associated with causing malignant hyperthermia in humans." (PMID 31304016, 2019). "Over 500 mutations have been mapped to RYRs and the majority of them are implicated in human diseases such as malignant hyperthermia as well as RYR1 myopathies, previously classified as central core disease (CCD) and multiminicore disease." (PMID 31395899, 2019). "Recurrent exertional rhabdomyolysis in horses is diagnosed when a horse that develops the condition tests negative for the Gys1 mutation associated with PSSM, as well as the RYR1 mutation associated with malignant hyperthermia." (PMID 31304016, 2019). "Type 1 RyR (RyR1) is a skeletal muscle isoform and mutations in RYR1 cause several muscle diseases, including malignant hyperthermia and central core disease." (PMID 30271978, 2018). "Recent findings indicate that several amino acid substitutions in mammalian skeletal muscle RYR1 are associated with malignant hyperthermia, environmental heat stroke, and exercise-induced rhabdomyolysis." (PMID 28576866, 2017). "The second variant, rs200563280, results in a premature stop codon in the RYR1 gene, a gene that is associated with malignant hyperthermia." (PMID 28502252, 2017). "In Pietrain pigs, mutations within the ryanodine receptor 1 (RYR1) are associated with malignant hyperthermia susceptibility (MHS), reduced water holding capacity, and increased PSE meat." (PMID 29070892, 2017). "Disease-causing mutations have also been identified in RyR1, and are linked to malignant hyperthermia or central core disease." (PMID 29235522, 2017). "Pathogenic variants in RYR1 are known to be associated with autosomal dominant, incomplete penetrance malignant hyperthermia as well as a number of muscle diseases such as centronuclear myopathy, central core disease, and multiminicore disease." (PMID 28361098, 2017). "In conclusion, our result confirms that LMPS is an allelic disorder of anaesthesia-related malignant hyperthermia, a group of congenital myopathies and foetal akinesia syndrome, associated with genetic defects in RYR1." (PMID 26932181, 2016). "Apart from congenital myopathy, heterozygous variants in RYR1 are known cause of susceptibility to malignant hyperthermia, a potentially lethal disorder of skeletal muscle calcium homeostasis." (PMID 26932181, 2016). "Mutations in the RYR1 gene yield RyR1 protein dysfunction that manifests clinically as RYR1-related congenital myopathies (RYR1-RM) and/or malignant hyperthermia susceptibility (MHS)." (PMID 27855725, 2016). "A group of congenital myopathy and anaesthesia-related malignant hyperthermia are allelic disorders associated with genetic defects in RYR1 (OMIM 180901)." (PMID 26932181, 2016). "The Repeat12 domain boasts positions for five malignant hyperthermia mutations in RyR1 and two CPVT mutations in RyR2." (PMID 26245150, 2015). "Mutations in RyR1 are associated with several muscle disorders, including malignant hyperthermia (MH) and central core disease (CCD)." (PMID 26115329, 2015). "Mutations in the RYR1 gene account for the majority of cases of malignant hyperthermia susceptibility (MHS) and central core disease (CCD) in humans." (PMID 26075051, 2015). "Mutation to the RyR1 gene in pigs has been previously correlated with the occurrence of malignant hyperthermia, a skeletal muscle myopathy, which leads to defects in Ca2+ channel functioning, PSE-type meat, and rigidity of the muscle caused by hypermetabolism." (PMID 25994290, 2015).